STRN4 (striatin 4)
Description:
Calmodulin-binding scaffolding protein which is the center of the striatin-interacting phosphatase and kinase (STRIPAK) complexes. STRIPAK complexes have critical roles in protein (de)phosphorylation and are regulators of multiple signaling pathways including Hippo, MAPK, nuclear receptor and cytoskeleton remodeling. Different types of STRIPAK complexes are involved in a variety of biological processes such as cell growth, differentiation, apoptosis, metabolism and immune regulation (Probable). Key regulator of the expanded Hippo signaling pathway by interacting and allowing the inhibition of MAP4K kinases by the STRIPAK complex.
Synonyms: ZIN; PPP2R6C; zinedin
Tractability: PROTAC: ubiquitination databases record sites on it; its protein half-life has been measured.
Gene: Protein-coding gene on chromosome 19 (46,719,511 to 46,746,994, reverse strand). Ensembl gene ENSG00000090372.
Subcellular location: Cytoplasm
Subcellular location (Human Protein Atlas): Cytosol
Gene Ontology:
Molecular function: armadillo repeat domain binding; protein binding; protein phosphatase 2A binding; protein-containing complex binding; protein-macromolecule adaptor activity; calmodulin binding; protein domain specific binding
Biological process: negative regulation of hippo signaling; regulation of hippo signaling; regulation of modification of postsynaptic structure
Cellular component: cytoplasm; FAR/SIN/STRIPAK complex; dendrite; neuronal cell body; postsynapse; dendritic spine; GABA-ergic synapse; glutamatergic synapse; protein-containing complex
Genetic constraint (gnomAD): Loss-of-function variants: 27 observed, 71.22 expected, observed/expected ratio (o/e) 0.38, 90% interval 0.28 to 0.52. The upper end of that interval is the gene's LOEUF score, 0.52, which puts it in group 2 of 6, group 1 being the genes least tolerant of losing a copy. Missense variants: 798 observed, 982.32 expected, observed/expected ratio (o/e) 0.81, 90% interval 0.77 to 0.86. Synonymous variants: 466 observed, 424.15 expected, observed/expected ratio (o/e) 1.1, 90% interval 1.02 to 1.19.
Homologues: Orthologues: chimpanzee STRN4 (99% identical), macaque STRN4 (99% identical), pig STRN4 (96% identical), dog STRN4 (95% identical), mouse Strn4 (95% identical), rat Strn4 (95% identical), guinea pig STRN4 (94% identical), rabbit STRN4 (74% identical), zebrafish strn4 (62% identical), Drosophila melanogaster Cka (45% identical), Caenorhabditis elegans cash-1 (34% identical). Paralogues in human: STRN3 (55% identical), STRN (53% identical).
Diseases named in the same sentence as STRN4 in open-access papers:
STRN4 is named in the same sentence as 22 diseases in open-access papers, as found by Europe PMC text mining. Sharing a sentence is not in itself a finding about the gene and the disease. The quoted sentences say what the papers report.
liver cancer (3 papers, 2021). An epithelial or non-epithelial malignant neoplasm that arises from the liver. "Additionally, correlation analysis found a negative association between the expressions of miR-3196 and STRN4 in liver cancer cells." (PMID 34386494, 2021). "Here we demonstrate that targeting STRN4 resulted in decreased tumorigenicity of liver cancer cells." (PMID 34375307, 2021). "Based on the results, we concluded that MAFG-AS1 regulates the progression of liver cancer cells through the miR-3196/STRN4 axis." (PMID 34386494, 2021). "Due to its numerous signaling complexes, STRN4 has been reported to be involved in the tumorigenesis of various cancer types, including colon cancer, liver cancer and prostate cancer." (PMID 33692863, 2021). "Our data hinted that MAFG-AS1 regulated HCC cell growth and migration through the miR-3196/STRN4 axis, exposing a potential neo-biomarker for diagnosis or treatment for liver cancer patients." (PMID 34386494, 2021). "The results showed that the miR-3196 inhibitor significantly reversed liver cancer cell migration, while STRN4 knockdown enhanced this effect." (PMID 34386494, 2021). "Thus, our study potentially provides the first evidence that STRN4 indeed possesses oncogenic properties in liver cancer." (PMID 34375307, 2021). "In order to investigate whether MAFG-AS1 affects the drug-resistant liver cancer cell lines by regulating the miR-3196/STRN4 pathway, we manipulated the expression of miR-3196 and STRN4 with miR-3196 inhibitor and sh-STRN4, respectively." (PMID 34386494, 2021).
pancreatic cancer (3 papers, 2020 to 2025). "In limited research on STRIPAK members in pancreatic cancer, the expression of STRN4 was found to be associated with reduced cell growth and spreading both in vitro and in vivo in mice." (PMID 38201504, 2023). "The lncRNA MAFG-AS1 has been shown to promote cell proliferation and migration in drug-resistant hepatocellular carcinoma (HCC) and pancreatic cancer by sponging miR-3196, leading to the upregulation of STRN4 and NFIX, respectively." (PMID 40004152, 2025). "Knocking down STRN4 sensitised pancreatic cancer cells to gemcitabine." (PMID 38201504, 2023). "Furthermore, silencing of STRN4 was shown to sensitise pancreatic cancer cells to gemcitabine." (PMID 38201504, 2023). "Indeed, STRN4 is highly expressed in a variety of tumour cells, and STRN4 knockdown suppresses the proliferation, invasion, and metastasis of cancer cells both in vitro and in vivo and increases the sensitivity of pancreatic cancer cells to gemcitabine in vitro." (PMID 32280692, 2020).
prostate carcinoma (3 papers, 2021 to 2024). A carcinoma that arises from epithelial cells of the prostate gland. "It has been reported that STRN4 promote cell proliferation and inhibit apoptosis in prostate cancer by regulating the leukaemia/lymphoma-related factor." (PMID 38215077, 2024). "Recent studies have revealed metastatic and protumorigenic properties of STRN4 in several tum or etiologies including colorectal and prostate cancer as well as non–small cell lung cancer (NSCLC)." (PMID 34375307, 2021).
bladder cancer (2 papers, 2021 to 2023). "The present study investigated the prognostic role of STRN4 in bladder cancer and aimed to determine the association between STRN4 and recurrence." (PMID 33692863, 2021). "High STRN4 expression in patients with high grade bladder carcinoma was 84.2% (59/70) compared with 57.1% (24/42) in patients with low grade bladder carcinoma." (PMID 33692863, 2021). "However, the prognostic role of STRN4 in bladder cancer is unclear and needs to be further determined." (PMID 33692863, 2021). "Although the specific biological mechanisms of STRN4 in bladder cancer still remain to be elucidated, STRN4 expression could be a prognostic indicator in bladder cancer." (PMID 33692863, 2021). "Taken together, the present results demonstrated that STRN4 may be a potential indicator for the prognosis of patients with bladder cancer and could be a new therapeutic target." (PMID 33692863, 2021). "Moreover, the present study analyzed STRN4 mRNA expression of patients with bladder carcinoma from the epidemiology and statistics database from the School of Public Health, Jilin University." (PMID 33692863, 2021). "However, to the best of our knowledge, there are no studies investigating the expression pattern of STRN4 in bladder cancer and the association between and STRN4 expression and prognosis." (PMID 33692863, 2021). "However, few studies on STRN4 have been conducted in bladder cancer, and its prognostic role in bladder cancer remains unknown." (PMID 33692863, 2021).
colorectal cancer (2 papers, 2019 to 2023). A primary or metastatic malignant neoplasm that affects the colon or rectum. "In colorectal cancer (CRC), knocking down STRN4 was shown to reduce the proliferation of colorectal cancer cells by modulating both cell cycle progression and apoptosis." (PMID 38201504, 2023).
hepatocellular carcinoma (2 papers, 2021 to 2025). A malignant tumor that arises from hepatocytes. "We silenced STRN4 expression in hepatoma cell lines Huh7 and Hep3B by siRNA." (PMID 34375307, 2021).
non-small cell lung carcinoma (2 papers, 2021). A group of at least three distinct histological types of lung cancer, including non-small cell squamous cell carcinoma, adenocarcinoma, and large cell carcinoma. "For example, miR-29b overexpression suppressed proliferation, migration, and invasion of non-small cell lung cancer cells by reducing Striatin 4 (STRN4) expression." (PMID 33601338, 2021).
asthma (1 paper, 2023). "Among the differentially co-expressed genes, eight were previously linked to asthma in genome- (MRPL14, ASB3, RHOBTB2) and epigenome-wide (CLC, EPS15, GPI, SSCRB4, STRN4) association studies and five were mentioned in the literature in the context of asthma (SLC19A1, MAEA, CLC, ATP1B1, and RECK)." (PMID 36835202, 2023). "Moreover, the differentially co-expressed genes, both up- and down-regulated in EA, were previously linked to asthma in the genome- (e.g., MRPL14, ASB3, RHOBTB2) and epigenome-wide (e.g., CLC, EPS15, GPI, SRCRB4D, STRN4) association studies." (PMID 36835202, 2023).
bladder transitional cell carcinoma (1 paper, 2021). The most common morphologic subtype of urinary bladder carcinoma (over 90% of cases). "Using multivariate analysis, it was reported that STRN4 was an independent prognostic biomarker for survival time in bladder transitional cell carcinoma." (PMID 33692863, 2021). "The present study aimed to investigate the expression levels of STRN4 in bladder transitional cell carcinoma and evaluate the prognostic role of STRN4." (PMID 33692863, 2021). "In summary, these results suggested that STRN4 is overexpressed in human bladder transitional cell carcinoma." (PMID 33692863, 2021).
bladder tumor (1 paper, 2021). "In order to determine STRN4 expression in bladder transitional cancer, IHC was performed on 28 pairs of fresh bladder tumor samples." (PMID 33692863, 2021).
gastric cancer (1 paper, 2023). A primary or metastatic malignant neoplasm involving the stomach. "Recently, targeting STRN4 by microRNA-6165, resulting in reduced STRN4 production, was also shown to suppress gastric cancer cell migration and invasion." (PMID 38201504, 2023).
heart failure (1 paper, 2024). Inability of the heart to pump blood at an adequate rate to meet tissue metabolic requirements. "Thus, although STRN and STRN3 have a similar profile overall with up-regulation in disease, STRN4 may have more specific and selective roles in different forms of heart failure." (PMID 38718356, 2024).
skin cancer (1 paper, 2021). "Across cancer types, STRN4 had a robust performance, which is in contrast to SOX10 that had a largely improved performance in skin cancer when compared to other cancer types." (PMID 33842927, 2021).
tumor (13 papers, 2019 to 2025). "Lu and colleagues discovered that mice deficient in macrophage PP2A exhibited reduced tumor progression through modulation of the PP2A/STRN4-YAP/TAZ axis." (PMID 39759159, 2025). "STRN4 was significantly associated with tumor size, muscle infiltration, pathological grade and microvascular invasion." (PMID 33692863, 2021). "It was demonstrated that STRN4 expression was significantly associated with clinical parameters such as tumor size, muscle invasion depth and pathological tumor grade." (PMID 33692863, 2021). "STRN4 expression was significantly associated with tumor size (P=0.005564), muscle infiltration (P=0.000357), pathological tumor grade (P=0.001500) and microvascular invasion (P=0.034741)." (PMID 33692863, 2021). "Our study provides significant insights by elucidating a novel molecular mechanism through which DHHC9 drives tumour progression via STRN4 palmitoylation, leading to phosphatase‐mediated YAP dephosphorylation and activation." (PMID 40903842, 2025). "We also demonstrated that PP2A/STRN4 deficiency in macrophages reduced YAP/TAZ expression and sensitized tumor-conditioned macrophages to STING stimulation." (PMID 36757811, 2023). "In summary, we demonstrated that PP2A/STRN4-YAP/TAZ has, in our opinion, been an unappreciated mechanism that mediates immunosuppression in tumor-associated macrophages, and targeting the PP2A/STRN4-YAP/TAZ axis can sensitize tumors to immunotherapy." (PMID 36757811, 2023). "We provide evidence that by inhibiting PP2Ac or its regulatory partner, STRN4, the tumor-induced brake on Hippo signaling can be relieved, leading to enhanced STING-Type I IFN response." (PMID 36757811, 2023). "Complicating this approach further is that certain PP2A holoenzymes are important for its tumor-suppressive activity, while other holoenzymes promote oncogenic transformation (such as STRN4)." (PMID 36328247, 2022). "Mechanistically, MAP4K4 interaction with STRN3 and STRN4 represses canonical MAP4K4 activity towards Hippo tumor suppressor pathway activation by bringing the kinase in proximity of PP2A." (PMID 35941177, 2022). "In order to investigate the association between STRN4 expression and specific clinical parameters, certain features such as age, sex, tumor size and muscle infiltration were chosen to measure the effects of STRN4 expression." (PMID 33692863, 2021). "Using publicly available databases, we confirmed upregulated expression of STRN4 in several tumor types, including HCC." (PMID 34375307, 2021). "STRN4 was detected in 77.5% (69/89) of cases with deep muscle infiltration (T2-T4) compared with superficial tumor invasion (Ta-T1), which was 39.1% (9/23)." (PMID 33692863, 2021). "Collectively, these observations demonstrate that STRN4 is required for ST-mediated transformation and tumor formation." (PMID 31913126, 2020). "Tumor volume as a function of time (E) or at the endpoint at day 21 (F) for subcutaneous xenografts expressing shLuc control or STRN4 shRNA (shSTRN4-58) in HEK TER ST cells (Student’s t-test, **p<0.001, ****p<0.00001)." (PMID 31913126, 2020). "We assessed the consequences of knocking down STRN4 in vivo and found that STRN4 knockdown significantly reduced tumor formation of HEK TER ST cells." (PMID 31913126, 2020). "Silencing of the STRN4 protein in many tumour cells can inhibit their proliferation, invasion, and migration." (PMID 32280692, 2020). "Ultimately, we identified ELK1 and STRN4 as downstream target genes for miR-873 to exert its tumor-suppressive roles." (PMID 31289617, 2019). "Indeed, we detected upregulated gene expression of STRN4 in several tumor types, including HCC in the TCGA database." (PMID 34375307, 2021). "STRN4 is required for ST-mediated transformation and tumor induction." (PMID 31913126, 2020).
tumor (continued). "Furthermore, since the main metastasis approach for bladder transitional carcinoma is still muscle intrusion, these results suggested that STRN4 is important in tumor metastasis and recurrence, and may serve as an effective indicator for progression." (PMID 33692863, 2021). "Furthermore, we revealed that miR-873 acted as a tumor-suppressive microRNA by directly binding to the 3ʹUTRs of ELK1 and STRN4 and suppressed their expression." (PMID 31289617, 2019). "Striatin 4 was recruited by SV40 ST to the Striatin Interacting Phosphatase and Kinase (STRIPAK) complex that redirects PP2A function toward the dephosphorylation of MAP4K4, leading to the activation of YAP1 and the inactivation of Hippo tumor-suppressive function." (PMID 36328247, 2022).
cancer (12 papers, 2019 to 2025). A tumor composed of atypical neoplastic, often pleomorphic cells that invade other tissues. "Similarly, cancer autoantibody biomarkers, such as SH3GL1-Abs and striatin 4-Abs, were associated with high antigen expression in the cancer tissues." (PMID 38732153, 2024). "In this study, we identified DHHC9 as a key driver of adenocarcinoma metastasis and demonstrated its essential role in promoting cancer cell migration through STRN4 palmitoylation." (PMID 40903842, 2025). "Loss of STRN4 palmitoylation disrupted YAP nuclear localisation and suppressed the expression of Hippo pathway targets, thereby inhibiting cancer cell migration." (PMID 40903842, 2025). "STRN4 belongs to the striatin family and functions as a co-factor, particularly in cancer-related pathways in prostate, lung, and gastric cancers." (PMID 35273597, 2022). "STRN4 was significantly overexpressed in cancer samples (43 cases) compared with ANCT (23 cases) (P<0.001)." (PMID 33692863, 2021). "Accumulating evidence has indicated that STRN4 participates in the development of various cancer types and cardiac dysfunction via STRIPAK and STRIPAK-like complexes." (PMID 33692863, 2021). "In addition, STRN4 mRNA expression analysis was performed using 43 cancer samples and only 23 ANCT samples." (PMID 33692863, 2021). "Other targets of LRF/ZBTB7A-mediated regulation of oncogenesis include Striatin 4 (STRN4), a protein implicated in the progression of various human cancers and protein C-ets-1 (ETS-1), which is overexpressed in several cancers and implicated in cell proliferation, apoptosis, invasion, and migration." (PMID 31823818, 2019). "By integrating proteomic analysis with functional assays, we provide compelling evidence that DHHC9‐mediated STRN4 palmitoylation facilitates YAP nuclear localisation, thereby enhancing YAP/TAZ signalling and ultimately driving cancer cell migration." (PMID 40903842, 2025). "It is highly expressed in a variety of cancer cells including HCT116 and knockdown of STRN4 dramatically decreases proliferation and migration of HCT116 cells." (PMID 31289617, 2019). "The STRN4 palmitoylation reduced YAP phosphorylation, promoted nuclear translocation of YAP and activated downstream Hippo pathway transcriptional targets—including CCN1, CCN2 and ANKRD1—thereby driving cancer cell migration." (PMID 40903842, 2025). "This interaction is regulated by STRN4 (or zinedin), a member of the striatin-interacting phosphatase and kinase (STRIPAK) complexes, which act as general regulators of a range of pathways active in cancer development." (PMID 35119068, 2022).
adenocarcinoma (1 paper, 2025). A common cancer characterized by the presence of malignant glandular cells. "In conclusion, our study provides critical insights into the role of DHHC9 in adenocarcinoma metastasis and highlights its potential as a therapeutic target through the inhibition of STRN4 palmitoylation and YAP activation." (PMID 40903842, 2025). "These underscore intervening DHHC9 or STRN4 palmitoylation as promising therapeutic strategies for combating Hippo‐YAP‐driven adenocarcinoma metastasis." (PMID 40903842, 2025). "We hypothesised that DHHC9‐mediated palmitoylation of STRN4 might regulate its migratory function in adenocarcinoma." (PMID 40903842, 2025). "In conclusion, we identified Treprostinil and 10‐HCPT as promising DHHC9 inhibitors, capable of suppressing adenocarcinoma cell migration by blocking the palmitoylation of DHHC9 and its substrate STRN4." (PMID 40903842, 2025). "Critically, this defines the DHHC9‐STRN4‐YAP axis, establishing a direct mechanistic link between palmitoylation and metastatic potential in adenocarcinoma, while reinforcing STRN4's scaffolding role within the STRIPAK complex." (PMID 40903842, 2025).
neurological disease (1 paper, 2017).
STRN4 also shares sentences with these, for which no sentence is quoted: colon cancer (2 papers); airway hyperresponsiveness (1); COVID-19 (1); leukaemia (1); medulloblastoma (1).